GPX4 (glutathione peroxidase 4)
Diseases named in the same sentence as GPX4 in open-access papers (continued):
Sharing a sentence is not in itself a finding about the gene and the disease.
tumor (continued). "Experimental studies showed that the GPX4 protein expression level was significantly decreased in tumor cells treated with RSL3, accompanied by mitochondrial membrane potential collapse, ROS surge, and iron ion metabolism imbalance, which all point to the typical phenotype of ferroptosis." (PMID 40559667, 2025). "Additionally, USP24 knockdown enhanced the anti-tumor effects of other GPX4 inhibitors, including ML162, ML210, and FIN56, in MDA-MB-231 cells, while exerting minimal impact on erastin-induced ferroptosis." (PMID 40715045, 2025). "Importantly, it also helped to unveil novel metabolic vulnerabilities that can be used to treat tumours refractory to therapies, as is the case for GPX4 inhibition in tumours with high rates of lipid peroxidation." (PMID 40136651, 2025). "CQD is an old anti-infection drug with safety, which could promote the levels of ROS and ferrous ions in tumor cells, while inhibiting GPX4 and increasing oxidative stress." (PMID 40298634, 2025). "Tumor cells exhibiting mesenchymal or hypoxic signatures demonstrate GPX4 dependency for survival." (PMID 40895556, 2025). "However, certain tumor cell lines remain resistant to ferroptosis despite complete GPX4 inhibition, suggesting the existence of compensatory regulatory mechanisms independent of GPX4." (PMID 40862825, 2025). "This “mild regulation” mode may reduce the toxic side effects of traditional GPX4 inhibitors while maintaining selective pressure on tumor cells." (PMID 40559667, 2025). "Taken together, these observations indicate that FSP1 and GPX4 cooperatively establish a dual-layer antioxidant defense system in PDAC cells, enabling KRAS-mutated tumor cells to bypass the “ferroptosis checkpoint” and facilitating their survival and proliferation." (PMID 40862825, 2025). "For example, mitochondria-targeting fatty acids were shown to inhibit tumor growth by inducing mitochondrial lipid peroxidation and GPX4 degradation, which provides a theoretical basis for the design of marine-derived mitochondria-targeting ferroptosis inducers." (PMID 40559667, 2025). "In the quest for marine-derived compounds to regulate tumor ferroptosis, a technology-driven screening strategy provided key methodological support for the discovery of lead molecules with lipid peroxidation and GPX4 signaling regulatory activities." (PMID 40559667, 2025). "We speculate that the increased IFN-γ promotes tumor ferroptosis, induced by the suppression of the Nrf2/HO-1/GPX4 axis." (PMID 40539046, 2025). "Furthermore, the combination of ML‐210 and ED‐71 also synergistically inhibited tumour growth (synergy index > 10), as the simultaneous inhibition of GPX4 and GPX1 disrupts their compensatory responses, offering a promising strategy for cancer therapy." (PMID 40259435, 2025). "There was also a significant decrease in Gpx4-positive osteocytes in tumor metastatic bone." (PMID 39814705, 2025). "Thus, it’s critical to comprehend GPX4’s molecular makeup, role, and regulatory method on tumor cells." (PMID 40969276, 2025). "Indeed, numerous studies have shown that disrupting NRF2 or GPX4 signaling can restore ferroptotic sensitivity in resistant tumor cells." (PMID 40885710, 2025). "In addition, RSL3-loaded nanoparticles promote tumor cell ferroptosis through GPX4 inhibition and elevate antitumor immune response." (PMID 40636119, 2025). "RSL3, aninhibitor of GPX4, suppressed tumor growth in athymic nude mice." (PMID 40264585, 2025). "Importantly, we show that INHBA maintains mitochondrial SLC25A10 stability, thereby activating the succinate/SUCNR1 axis and the mtGSH/GPX4 axis to promote tumor malignancy." (PMID 41449244, 2025).
tumor (continued). "Moreover, tumor tissues from tumor-bearing mice also exhibited low kynurenine levels following GPX4 knockdown." (PMID 40365295, 2025). "This evidence demonstrated that the role of GPX4 is in regulating tumor immune cell infiltration." (PMID 40746894, 2025). "In cancer progression, lncRNAs could orchestrate GSH dynamics by regulating NRF2-targeted antioxidant genes and GPX4 expression, respectively, thereby influencing oxidative stress adaptation and tumor growth." (PMID 40403492, 2025). "Notably, IL-1β is upregulated during GPX4-deficient Treg ferroptosis, which subsequently activates DCs and CD8 + T cells, leading to suppressed tumor growth." (PMID 41326356, 2025). "Additionally, Bufotalin is emerging as a potential anti-tumor agent targeting ferroptosis by promoting the ubiquitination of GPX4 and increasing the intracellular Fe2+ level in NSCLC cells." (PMID 40427734, 2025). "GPX4 is a key target for tumor cell multiplication, differentiation, migration, and invasion." (PMID 40969276, 2025). "To verify whether ferroptosis also occurred in our animal experiments, we examined the mRNA and protein expression of Slc7a11 and Gpx4 genes in the tumour tissues." (PMID 41451920, 2025). "A growing body of research has confirmed that GPX4 is crucial in cancer biology, encompassing tumor viability, migration and invasion, response to chemotherapy and modulation of the tumor immune microenvironment." (PMID 41142608, 2025). "Therefore, the decrease in GPX4 suggested that the cellular defense mechanism against ferroptosis was suppressed, potentially enhancing the sensitivity of tumor cells to TRT." (PMID 40968370, 2025). "FK866 suppressed tumor growth in mice, and immunohistochemical staining of Ki67 and Gpx4 revealed that FK866 could inhibit cell proliferation and promote ferroptosis." (PMID 40492508, 2025). "Several types of tumor cells may undergo ferroptosis and generate toxic lipid ROS if GPX4 activity is inhibited, while xCT is an antiporter protein on the cell membrane that controls the homeostasis of glutathione and cysteine in cells." (PMID 40427585, 2025). "Tumor cells often exist in highly oxidative environments, where the antioxidative effects of GPX4 may contribute to their survival." (PMID 40191731, 2025). "The observed superior activity of RSL3 suggests that direct GPX4 inhibition may more effectively bypass compensatory antioxidant mechanisms induced by the tumor microenvironment." (PMID 40524253, 2025). "This suggests a potential regulatory paradigm, where miRNA-GPX4 interactions may exhibit tissue-specific or tumor-type selectivity, and further studies are required to confirm the interaction between miRNAs and GPX4 in COAD." (PMID 40746894, 2025). "Consequently, GSH, SLC7A11, and GPX4 can be deemed as negative regulatory proteins for ferroptosis in tumor cells." (PMID 39822985, 2025). "In addition, GPX4 affects macrophage polarization, promoting the conversion from protumor M2 macrophages to tumor‐suppressing M1 macrophages, thereby enhancing antitumor immune responses." (PMID 40599237, 2025). "Polyamines have been reported to bind directly to GPX4 and stabilize the protein, protecting it from proteasomal degradation; dysbiosis that perturbs polyamine pools can therefore alter GPX4 half-life and shift tumor cell sensitivity to ferroptotic stimuli." (PMID 41301464, 2025). "Notably, the level of Gpx4 in tumor from patients with advanced CRC has been found to be obviously higher than that in para‐cancer tissues." (PMID 39846413, 2025). "By suppressing ferroptosis, GPX4 protects tumor cells and contributes to tumor development." (PMID 40191731, 2025). "Hence, GPX4 is an intrinsic critical determinant for preventing Treg ferroptosis and restraining immune activation in the progression of tumours." (PMID 40045458, 2025).
tumor (continued). "GPX4 functions to prevent Treg cells from undergoing lipid peroxidation and ferroptosis, thereby exerting a protective role in maintaining immune homeostasis and potentiating anti-tumor immunity." (PMID 40260246, 2025). "Overall, these findings suggest that GPX4 knockdown in tumor cells may inhibit macrophage M2 polarization by lowering kynurenine levels in the cellular environment." (PMID 40365295, 2025). "Additionally, Western blot and IHC analysis of tumor tissues revealed a marked reduction in GPX4 expression in the GLS-knockdown group, suggesting an enhanced level of ferroptosis." (PMID 40308578, 2025). "The results showed that the expression levels of NRF2, GCLM and GPX4 were significantly increased after intervention with RT + Fer-1 or RT + TBHQ compared with the RT group in tumor tissues of the two ESCC cell lines, and there were statistical differences in all of them." (PMID 40707557, 2025). "Moreover, IHC analysis of subcutaneous xenograft tumor tissues revealed that the expression of PP1A was positively correlated with that of GPX4 and NQO1, which are crucial for ferroptosis." (PMID 40344394, 2025). "Core regulators of ferroptosis, such as GPX4 and SLC7A11, are highly expressed in various GI tumors and are associated with poor prognosis; inhibiting their function can effectively trigger lipid peroxidation-mediated death in tumor cells." (PMID 41201667, 2025). "Pharmacological inhibition of GLS1 synergises with GPX4 inhibitor to suppress tumour growth." (PMID 40259435, 2025). "Immunohistochemistry staining of tumor tissues showed an obvious downregulation of GPX4 for MSF + US and MSF@CCM + US groups, implying MSF and MSF@CCM could effectively induce ferroptosis and further enhanced with the assistance of US." (PMID 40274835, 2025). "Furthermore, the expression of Nrf2, HO‐1, and Gpx4 protein in primary tumor tissues was downregulated by the Mon treatment." (PMID 40439491, 2025). "or fermentation substrates (dietary fibers) aims to enrich SCFA-producing taxa that both (a) downregulate tumor antioxidant defenses (GPX4/SLC7A11) and (b) favor DC maturation and CD8+ T-cell priming—thereby lowering tumor ferroptosis thresholds while augmenting antitumor immunity." (PMID 41301464, 2025). "Tumour tissues from treated PDX models have notably shown reduced GPX4 expression." (PMID 40143107, 2025). "Taken together, our observations, coupled with existing literature, suggest that GPX4-driven poor prognosis may be the result of its dual role in intrinsic tumor cell protection and extrinsic immune suppression." (PMID 40746894, 2025). "It was observed that in vivo tumour development was inhibited by GPX4 suppression." (PMID 41451920, 2025). "By suppressing ferroptosis, GPX4 counteracts tumor development and protects tumor cells." (PMID 40191731, 2025). "Notably, in tumor models where GPX4 activity is suppressed, the high expression of TfR1 accelerates the accumulation of lipid peroxidation products, which eventually leads to the irreversible disruption of the cell membrane integrity." (PMID 40559667, 2025). "Furthermore, bromophenolic compounds isolated from red algae were shown to specifically enhance the sensitivity of tumor cells to GPX4 inhibitors by hijacking the mitochondrial CoQ10 synthesis pathway." (PMID 40559667, 2025). "We further investigated whether GPX4 expression in tumor cells affects macrophage polarization and, consequently, tumor cell behavior." (PMID 40365295, 2025).
tumor (continued). "The GPX4 tumor regulating mechanism is dependent on the modulation of ferroptosis." (PMID 40969276, 2025). "We investigated the expression of NFE2L1 and GPX4 in both normal and tumor tissues." (PMID 41189569, 2025). "Additionally, both in vitro and in vivo functional studies were conducted to elucidate the mechanistic role of GPX4 in regulating the tumor microenvironment and progression." (PMID 40365295, 2025). "In CRC, miR-15a-3p decreased tumor development by reducing GPX4 expression, promoting ferroptosis." (PMID 40403492, 2025). "Moreover, we detected that the levels of Ki67 and GPX4 were decreased, whereas the level of cleaved Caspase3 was elevated in tumor tissues from the MET/Fast group, indicating weakened proliferation and increased apoptosis and ferroptosis." (PMID 39937004, 2025). "However, the sensitivity of different tumor cells to GPX4 inhibitors varies greatly, indicating that other factors determine the resistance of tumor cells to ferroptosis." (PMID 39744575, 2025). "Thus, dysregulated GPX4 contributes to ferroptosis with significant implications for potentially overcoming tumor drug resistance." (PMID 40298634, 2025). "Moreover, we examined OTUD5 and GPX4 protein levels in different groups of MFC tumour tissues collected." (PMID 40070026, 2025). "Therefore, targeting GPX4 has emerged as a viable strategy to enhance ferroptosis-mediated tumor cell death in resistant tumor cells." (PMID 39935430, 2025). "used the Foxp3YFP-Cre Gpx4FL/FL mouse model and found that GPX4-specific deletion in Tregs leads to lipid peroxide accumulation and triggers ferroptosis, accompanied by an increase in the proportion of Th17 cells and an enhanced anti-tumor immune response." (PMID 40535125, 2025). "Previous studies have proposed that targeting SLC7A11 or GPX4 may enhance tumor cell sensitivity to chemotherapy and radiation by inducing ferroptosis." (PMID 40113760, 2025). "Furthermore, the ability of α4-1BB treatment to promote proliferation and IFN-γ production in vitro and in vivo is abrogated in antigen-specific GPX4–/– CD8+ T cells compared with WT T cells from tumor-bearing mice." (PMID 40178905, 2025). "The current study shows that GPX4 in tumor cells regulates the ubiquitination and expression of the lesser-studied enzyme KYNU in the kynurenine pathway by controlling intracellular ROS levels, affecting kynurenine levels in the TME and ultimately affecting macrophage polarization." (PMID 40365295, 2025). "Our findings reveal that BSN blocks CRC growth by inducing p62/NRF2/GPX4‐regulated ferroptosis, which may be a novel lead compound for tumor treatment." (PMID 39846413, 2025). "Notably, functional studies in melanoma and non-small cell lung cancer have demonstrated that GPX4 inactivation can induce persistent tumor ferroptosis in vitro, suggesting its potential as a critical therapeutic target." (PMID 40298634, 2025). "This suggests that GPX4 could be a therapeutic target for modulating the tumor immune microenvironment." (PMID 41142608, 2025). "Inhibiting GPX4 is a more direct way to suppress tumor progression by inducing ferroptosis." (PMID 41318030, 2025). "An important finding of our study is that GPX4 overexpression likely reduced CTLs infiltration, which could attenuate the response to immunotherapy and strengthen the protection of tumor cells." (PMID 40746894, 2025). "K-SAN effectively induces ferroptosis in tumor cells by initiating a reactive oxygen species storm and depleting reductive glutathione, which leads to the accumulation of lipid peroxides and the inactivation of glutathione peroxidase 4 (GPX4)." (PMID 40510836, 2025). "Herein, CAE pre- and post-treatments significantly decreased MDA levels, while enhancing the activities of ROS scavenging enzymes, including SOD, CAT, GPx, GRD, and elevated TAC in tumor tissues, and enhanced the expression of the antioxidant enzyme Gpx4 at the mRNA levels." (PMID 40898252, 2025).
tumor (continued). "Interestingly, immunohistochemical staining for GPX4 in tumor tissues revealed a significant decrease in GPX4 expression after treatment with 131I-Mn/SAE@M." (PMID 40968370, 2025). "Thus, more research can look at the potential for tumor-targeted treatments, including how GPX4 and other cell death mechanisms are regulated, as well as how GPX4 inhibitors and immune checkpoint inhibitors work in concert." (PMID 40969276, 2025). "Furthermore, RNA extraction and subsequent qPCR experiments were performed to evaluate the Nrf2/HO-1/GPX4 pathway in tumor tissues." (PMID 40539046, 2025). "Thus, impairment of the GSH/GPX4 axis facilitates ROS‐mediated ferroptosis, effectively suppressing tumor development through iron‐dependent oxidative destruction of malignant cells." (PMID 40599237, 2025). "Tumor cells usually exist in highly oxidative environments, where the antioxidative effects of GPX4 may contribute to their survival." (PMID 40191731, 2025). "Additionally, IHC analysis of vehicle and EC359 treated tissues using Ki-67 and GPX4 antibodies revealed decreased proliferation and reduced GPX4 levels in EC359-treated tumor tissues." (PMID 40075639, 2025). "Furthermore, GPX4’s control of ferroptosis in tumor cells is also significantly impacted by alterations in the microenvironment within those tumor cells, including variations in lipid peroxide and iron ion levels." (PMID 40969276, 2025). "A novel small molecule inhibitor (Bufotalin) of GPX4 was recently reported to induce GPX4 ubiquitination and degradation, lipid peroxidation, and ferroptosis, and thus could serve as potential anti-tumor agents." (PMID 37470788, 2024). "Taken together, we could conclude that the inhibitory impact of FASN on ferroptosis was achieved via NF-κB/STAT3/GPX4 axis, thereby facilitating tumor growth and resistance to ADM in DLBCL." (PMID 39345091, 2024). "Indeed, hypoxic conditions in the TME recapitulated the downregulation of GPX4 seen in PMN-MDSCs from the tumor compared to the spleen or bone marrow." (PMID 39188677, 2024). "GGT1, a member of the GGT family, has been shown to inhibit ferroptosis via the GSH/GPX4 axis and thus inhibit tumour progression 6, 29, and its amino acid sequence shares 34% homology with its fellow family member GGT7, the protein space structure also has similarity." (PMID 38911386, 2024). "The poor tumour delivery efficacy of GPX4 inhibitor has dampened its in vivo therapeutic value." (PMID 38212623, 2024). "In addition, Zou’s group reported the induction of tumor cell ferroptosis due to the suppression of the GSH/GPX4 axis by CD8+ T cell–mediated IFN-γ upon ICB, confirming a generalizable ferroptotic pathway also used by tumor cells for survival." (PMID 38441967, 2024). "Additionally, through further immunoblot analysis of tumor tissues, we observed that Formononetin treatment led to a reduction in the expression of intracellular ferroptosis-related proteins GPX4, and xCT." (PMID 39399463, 2024). "In this context, besides their well described effect on solid tumors, reprogramming tumor resident macrophages using GPX4 inhibitors could be of potential interest in solid cancer and hematopoietic malignancies including AML." (PMID 38977956, 2024). "In addition, reduced Cys, GSH, and GPX4 expression levels were observed in ANO6-plasmid treated xenograft tumor models." (PMID 38756246, 2024). "Interestingly, GPx4, further to being involved in lipid metabolism and the inhibition of ferroptosis, also plays a significant role in tumor vascularization." (PMID 39594547, 2024). "In activated Treg cells, GPX4 could be induced and then resisted ferroptosis, which leads to tumor immune escape." (PMID 38534739, 2024). "Additionally, in the gastric xenograft mouse model characterized by high ABCC2 expression, we noted that restricting amino acid intake in combination with GPX4 inactivation led to significant tumour regression." (PMID 39095325, 2024).